TDO2 (tryptophan 2,3-dioxygenase)
Diseases named in the same sentence as TDO2 in open-access papers (continued):
Sharing a sentence is not in itself a finding about the gene and the disease.
tumor (continued). "Amount of evidence suggest that IDO1- or TDO2-expressing tumor cells can escape immunosurveillance via Trp starvation, and AhR is involved in tumor immune evasion." (PMID 35173722, 2022). "The greater association of KAT 1 with the Trp transporters and TDO2 and FAMID further emphasises the importance of KA production for tumours." (PMID 36286592, 2022). "In conclusion, our current study demonstrates that TDO2 is a direct target of miR-126-5p which regulated tumor progression via influencing the PI3K/AKT and WNT1 pathway." (PMID 35056756, 2022). "The amino acid tryptophan was often depleted in the tumor microenvironment due to its catabolism by tryptophan 2,3-dioxygenase (TDO2) or indoleamine 2,3-dioxygenase (IDO1), resulting in the production of kynurenine." (PMID 36282248, 2022). "The oxidative Trp metabolic rate-limiting enzymes, IDO1 and TDO2, have been demonstrated to be constitutively expressed at high levels and are responsible for tumor growth and metastasis in several tumor types." (PMID 36172162, 2022). "The murine tumors showed that TDO2+ myofibroblasts were also mainly located in the distal area of the tumor nests and that CD4+ and CD8+ T cells were mainly located around TDO2+ myofibroblasts, consistent with the results observed in human OSCC tissues." (PMID 35972800, 2022). "As a part of concerted mechanisms that occur in the TME, a multitude of cancer cells constitutively express or upregulate IDO1, TDO2, or both, and coerce stromal and tumor-infiltrating immune cells to express IDO1, supporting evasion of immunosurveillance." (PMID 35173722, 2022). "It is reported that TDO2 is highly expressed in many tumors and promotes tumor progression, and as a promising cancer treatment target, it has attracted more and more attention." (PMID 36185201, 2022). "The first mechanism involves the overexpression of the rate-limiting enzymes IDO1 and TDO2 to deplete TRP within the tumour microenvironment." (PMID 34680327, 2021). "Despite the pro-tumor efficacy of IDO1 in tumor development and therapy, the role of TDO2, an IDO1 isozyme, remained poorly investigated." (PMID 34657635, 2021). "To compare the expression level of TDO2 in normal and tumor tissue, we retrieved the RNA-Seq data from TCGA RCC included in three databases: KIRC, KIRP, and KIRH." (PMID 34174844, 2021). "As the depletion of tryptophan and the production of its downstream metabolites can restrain the proliferation of immune cells, the overexpression of TDO2 in tumors was considered to promote tumor immune escape and stimulate cancer metastasis." (PMID 34423034, 2021). "Tumors overexpressing TDO2 are resistant to tumor rejection, and treatment with a TDO2 inhibitor reversed the ability of tumor rejection in immunized mice." (PMID 34174844, 2021). "CMG017 and CB548, two dual inhibitors of IDO1 and TDO2, have been shown to potently suppress the kynurenine pathway and they showed promising anti-tumor efficacy, with favorable pharmacologic profiles, overcoming resistance to immune checkpoint inhibitors." (PMID 33924971, 2021). "Further, dual IDO and TDO2 inhibitors are being explored that should completely block tumor production of Kyn." (PMID 34832904, 2021). "This was specific of HCC cells since TDO2 protein was barely detected in other tumor cells, but only in vascular structures in the tumors." (PMID 34943977, 2021). "TDO2 is mainly expressed in the liver; however, it has also been shown to be overexpressed in tumours as a means of immune evasion." (PMID 34053179, 2021). "IDO1 and TDO2 enzymes catalyze Trp oxidation to Kyn, which are frequently observed in tumor tissues and tightly correlated with the poor prognosis in patients." (PMID 34657635, 2021). "The expression of IDO1 in the majority of cancers is related to immunosuppression, which promotes tumorigenesis, while the expression of TDO2 is responsible for tumor invasion and proliferation." (PMID 34943977, 2021).
tumor (continued). "IDO (indoleamine 2,3-dioxygenase) and TDO (tryptophan 2,3 dioxygenase) convert the essential amino acid tryptophan to kynurenine, the latter having strong immunosuppressive activity and promoting tumor growth." (PMID 34344457, 2021). "Various studies have demonstrated the importance of KYN-AhR activation in IDO1- or TDO2-expressing tumour cells and its role in enhancing cancer cell survival and motility." (PMID 34680327, 2021). "This study demonstrated the immune-regulatory role of the TDO2 enzyme in HCC tumour cells, and suggested that the TDO2 enzyme was a promising immunotherapy treatment target for HCC." (PMID 34680327, 2021). "Increased tryptophan (Trp) metabolism by indoleamine 2,3-dioxygenase (IDO)/tryptophan 2,3-dioxygenase (TDO) represents one of the most studied pathways for immunosuppression in tumor tissues." (PMID 34657635, 2021). "Since the loss of TDO2 expression was correlated with adverse clinical outcomes and a poor prognosis in HCC, it is possible that TDO2 acts as a tumor suppressor." (PMID 34423034, 2021). "We then examined TDO2 protein expression in a clinical tissue microarray (TMA) and tissue specimens of HCC using immunohistochemical (IHC) staining and western blot analysis, which revealed lower TDO2 protein levels in tumor specimens than in normal tissues." (PMID 34423034, 2021). "In SMC-7721 and HepG2 cells, overexpression of TDO2 significantly strengthened the capability of colony formation in tumor cells." (PMID 34657635, 2021). "Consistently, activation of AhR/IL-6/STAT3/ NF-kB signaling was observed in TDO2 overexpression tumor tissues." (PMID 34657635, 2021). "TDO2 mRNA expression was detected in different types of tumours including hepatocarcinoma, glioblastoma, breast cancer, and colorectal cancer." (PMID 34680327, 2021). "TDO2 overexpression was shown to suppress anti-tumor immune responses in mouse models, and PD-L1, an immune checkpoint, was shown to be significantly upregulated in clear cell RCC." (PMID 34174844, 2021). "More recently, TDO2 has been shown to be expressed in many tumors and to promote tumor growth by suppressing antitumor immune responses in a similar fashion." (PMID 32477324, 2020). "Injection of mice, immunised against a major antigen of tumour P815 cells, with murine TDO2-overexpressing P815 cells led to the development of tumours." (PMID 31819194, 2020). "TDO2 has been demonstrated to have immunomodulatory functions in promoting tumor immune resistance, which drew increasing attention to target this pathway for cancer immunotherapy." (PMID 33542896, 2020). "Functionally and mechanistically, circZNF566 promotes HCC progression and metastasis via the circZNF566/miR-4738-3p/TDO2 axis, indicating its tumor promoter role in HCC development." (PMID 32532962, 2020). "IDO1/TDO2 inhibitors suppress tumor formation in animal models and are currently being evaluated in clinical trials against a wide range of cancers, including melanoma, glioblastoma, non–small cell lung cancer, and pancreatic and breast cancers." (PMID 32325928, 2020). "While in a nutrient-deficient hypoxic microenvironment, where hypoxia itself keeps the immune system in check, tumor cells in a HIF1α-dependent fashion can downregulate TDO2 expression so as to conserve Trp." (PMID 31866995, 2019). "TDO2 is an immunosuppressive enzyme, whose metabolic products have been shown to modulate anti-tumor immune responses by inhibition of T cell proliferation as well as induction of apoptosis in T cells." (PMID 31866995, 2019). "IDO1 and TDO2 are involved in catabolism of tryptophan (trp) which depletion in tumor microenvironment results in inhibition of T cell responses." (PMID 29285252, 2017). "IDO1 and TDO2 play important roles in mediating both tumor immunoescape and immune response regulation." (PMID 27578919, 2016). "Accordingly, active expansion of Tregs cells through KYN-AhR activation creates an immune suppressive zone around IDO1 and/or TDO2 expressing tumours." (PMID 26646699, 2016).
tumor (continued). "Over the past decade strong evidence has accumulated that confirms that IDO1/TDO2 overexpression in tumour results in tryptophan depletion in the microenvironment, in turn, suppressing the T-cell mediated immune response." (PMID 26646699, 2016). "Collectively, these studies highlight the importance of the AhR in IDO1 and/or TDO2 expressing tumours and emphasize the role that autocrine production of inflammatory cytokines plays in tumour survival and growth." (PMID 26646699, 2016). "Similar to CTLA-4, up-regulation of IDO1 or TDO2 allows tumor cells to evade antitumor immunity check from host T cells." (PMID 28027300, 2016). "The TDO-2-derived kynurenine then acts through the AHR in tumor cells in an autocrine manner and promotes tumor survival as well as altering the regional immune response by favoring Treg development." (PMID 25324842, 2014). "In addition, TDO2 is found to be expressed across multiple cancer types, which facilitates tumor immune escape and impairs T cell function." (PMID 41557627, 2026). "Tumor cells, tumor-associated macrophages, and certain dendritic cells can decrease local tryptophan levels by provoking metabolic enzymes, including indoleamine 2,3-dioxygenase (IDO1) and tryptophan 2,3-dioxygenase (TDO2)." (PMID 41179661, 2025). "Thus, the IDO1/TDO2–kynurenine axis serves as a metabolic immune checkpoint that promotes tumor immune escape." (PMID 41562065, 2025). "The level of TDO2 expression is positively correlated with the expression level of genes critical for uterine smooth muscle tumor growth, and the concentration of TDO2 is significantly elevated in uterine smooth muscle tumors with MED12 mutations, which further promotes tumor growth." (PMID 41282989, 2025). "Similarly, TDO2 overexpression correlates with tumor growth, progression, immune regulation, and poor outcomes in ESCC patients." (PMID 40821701, 2025). "As TDO2 has also been shown to promote tumor growth in some cancers, it is reasonable to speculate that TDO2 and IDO2 may act as compensatory pathways to continue KYN production and influence tumor immunity when IDO1 is inhibited." (PMID 40103267, 2025). "Finally, dual inhibition of IDO1/TDO2 in vivo reduced ID8 tumor growth, macrophage infiltration, PD-L1 expression, and extended overall survival in this preclinical model." (PMID 38451784, 2024). "Since the enzymatic activity of IDO1 and TDO2 have been shown to contribute to the immune-suppressive condition in the tumor microenvironment (reviewed in9), small molecule inhibitors are regarded as a therapeutic option to reinvigorate anti-tumor immunity." (PMID 39537789, 2024). "TDO2 OE was also sufficient to promote PD-L1 expression on HGSC tumor cells." (PMID 38451784, 2024). "TDO2 could be a target of miRNAs in HCC that promoted tumour cell proliferation, metastasis, and invasion." (PMID 39648156, 2024). "In the context of this cancer type, it has been reported that miR-126-5p promotes tumor cell proliferation, metastasis, and invasion by targeting tryptophan 2,3-dioxygenase (TDO2), which is a key enzyme in the tryptophan–kynurenine metabolic pathway (right bottom)." (PMID 38473229, 2024). "Tryptophan through its degradation by indoleamine-2,3-dioxygenase 1 (IDO1) and tryptophan-2,3-dioxygenase 2 (TDO2) to kynurenine has emerged as an important metabolic regulator of tumor progression, immune suppression and immune tolerance in the tumor microenvironment." (PMID 39450255, 2024). "Our studies further support the potential therapeutic efficacy of dual IDO1/TDO2 inhibition as a part of immuno-therapeutic treatment that enhances tumor immune surveillance and blocks tumor metabolism-related survival mechanisms in platinum-resistant NSCLC tumors." (PMID 37226257, 2023). "Importantly, while selective IDO1 inhibition attenuated CR tumor growth, it concomitantly upregulated the TDO2 enzyme." (PMID 37226257, 2023).
tumor (continued). "Moreover, overexpression of the tryptophan-transport- and metabolism-related genes SLC1A5, SLC7A5, SLC7A8, and TDO2 in tumor cells also provides potential strategies for cancer therapy." (PMID 37545500, 2023). "Following the co-expression and network analyses, this signature was found to be enriched for genes involved in the regulation of the stroma component of the tumor (TDO2, STEAP1) as well as Treg cells (SLC16A1, PRKAB1) and myeloid cell (APOBEC3A, MERTK, SNX29) subsets." (PMID 36216827, 2022). "To summarize, TDO2+ myofibroblasts were mainly located distally from tumor nests, and these cells attracted CD4+ T cells and CD8+ T cells through the CXCL9/CXCL10/CXCL11/CXCR3 axis, which may have prevented T cells from accessing tumor nests." (PMID 35972800, 2022). "The treatment with a TDO2 inhibitor could promote the function of dendritic cell and improve T cell mediated immune response, thereby diminishing tumor metastasis in mice." (PMID 36118672, 2022). "In addition, TDO2 has the function of transducing the tumor immune escape via the IDO1/TDO2–KYN–AhR signaling pathway." (PMID 36230866, 2022). "Growing evidence supports TDO2 as another Trp catabolic enzyme involved in immune escape and TDO2 inhibition could be a new immunomodulatory approach to strike tumor." (PMID 35173722, 2022). "To further investigate whether TDO2 inhibitors can inhibit tumor growth and promote anti–PD-1 efficacy, we constructed a subcutaneous tumorigenesis model in C57BL/6 mice inoculated with murine OSCC cells (4MOSC2)." (PMID 35972800, 2022). "The revealed features of TDO2—a significant increase in expression at the metastatic stage, the absence of other IC genes with correlated expression—indicate the prospect of inhibiting this gene in a metastatic GC tumor." (PMID 36430322, 2022). "Additionally, TDO2 expression was correlated with the development of the tumour, such as size, tumour differentiation, and vascular invasion." (PMID 34680327, 2021). "As the transcription factor AhR together with IDO1 and TDO2 are present in tumor cells, it has been proposed that KYN could have a dual role in promoting cancer invasion and immune escape." (PMID 34943977, 2021). "Besides IDO1 and Arg 1, other amino acid degrading enzymes such as tryptophan 2,3-dioxygenase and arginase 2, has relevance in the regulation of tumor-induced immune tolerance, including the induction of an immunosuppressive tumor microenvironment." (PMID 34389039, 2021). "This study also revealed new immune suppressive miR-200c targets that may dampen anti-tumor immunity in mTNBC, including tryptophan-2,3 dioxygenase (TDO2), chitinase-3 like-1 (CHI3L1) and heme oygenase-1 (HO-1)." (PMID 34832904, 2021). "Apart from IDO1, overexpression of TDO2 in tumour cells has been shown to facilitate immune escape." (PMID 34680327, 2021). "Given the key role that TDO2 plays in establishing the tryptophan-poor, immunosuppressive tumor microenvironment evident in the mesenchymal subtype of GBM – in which patient prognosis is particularly poor – our work uncovers a potential new target for therapeutic intervention." (PMID 32477324, 2020). "TDO2 was overexpressed in tumor tissue specimens obtained from UM hepatic metastasis and could be associated with the development and growth of metastasis in UM." (PMID 33542896, 2020). "Taken together, our data suggest that the regulation of TDO2 expression by HIF1α may be involved in modulating anti-tumor immunity in GBM." (PMID 31866995, 2019). "Several key pathway molecules in the tryptophan pathway, including IDO-1, TDO-2, and kynurenine, participate in controlling immune tolerance and promoting tumor escape by regulating T cells and the proliferation, differentiation, and apoptosis of tumor cells via the AhR." (PMID 29487603, 2018). "After IDO1 silencing, TDO2 may function as a compensatory mechanism to sustain tumor growth." (PMID 40103267, 2025).
tumor (continued). "In addition, among the LNCaP xenograft tumours we collected, both TDO2 and AhR proteins were significantly upregulated in tumours that recurred after castration compared with normal tumours, and the mRNA levels of TDO2, AhR, and CYP1A1 were also significantly elevated." (PMID 40759641, 2025). "The absence of association with IDO1 or TDO2 may indicate alternative activators within the tumour microenvironment." (PMID 40471422, 2025). "However, tumor cells and myeloid cells may express tryptophan 2,3-dioxygenase 2 (TDO2) and catabolize tryptophan via an alternative pathway that replaces or complements IDO1." (PMID 35571116, 2022). "Indeed, the TDO2-kynurenines-AhR axis had an immune regulatory role of restricting the activation of T cells, and TDO2 inhibitor treatment showed recruitment of the anti-tumor effect in mouse models." (PMID 34174844, 2021). "Moreover, targeting the IDO1/TDO2-kynurenine-AHR pathway to restore potent anti-tumor immune responses is an important goal of cancer immunotherapy, which might be highly relevant for HCC and cholangiocarcinoma therapy." (PMID 34075438, 2021). "However, TDO2 was shown to be overexpressed in some tumor cells as a mean of immune escape." (PMID 32733441, 2020). "Since tryptophan 2,3-dioxygenase (TDO) is predominantly expressed in the liver, we speculated that TDO encoded by the TDO2 gene might play a role in T-cell non-inflamed tumor microenvironment in the liver." (PMID 32050636, 2020). "At this moment, we are not sure whether expression of TDO2 RNA in high risk primary UM is related to molecular or genetic alternation in UM cells or in response to an inflammatory tumor microenvironment, as seen in Cluster 4 UM." (PMID 32050636, 2020). "This metabolic imbalance results from upregulated activity of tumor-promoting enzymes (IDO1, TDO2, KMO, KYNU) alongside downregulated protective enzymes(KATs, ACMSD)." (PMID 41602107, 2026). "The dual inhibitor RY103, which targets both IDO1/TDO2 and the KYN-AHR-AQP4 axis, has been shown to suppress tumor invasion and migration in GBM models." (PMID 41602107, 2026). "Among these, the enzymes indoleamine 2,3-dioxygenase (IDO) and tryptophan 2,3-dioxygenase (TDO), which mediate tryptophan catabolism, and the vascular endothelial growth factor (VEGF) axis play significant roles in immune evasion and tumor progression." (PMID 40725830, 2025). "Previous studies have found that the abnormal expression of TDO2 and IDO1 is related to tumor invasiveness." (PMID 40103267, 2025). "By suppressing both IDO1 and TDO2, DN1406131 13 attempts to prevent tryptophan depletion and kynurenine buildup within the tumor microenvironment, reactivating anti-tumor immunity." (PMID 41035912, 2025). "Key enzymes of the KYN pathway, including TDO2 and KMO, were upregulated in most early-stage tumours, consistent with previous transcriptomic and proteomic studies using IHC36,37." (PMID 40348885, 2025). "The enzymes IDO1 and TDO2 are considered key therapeutic targets in the KYN pathway due to their role in immune suppression and tumor progression." (PMID 39997327, 2025). "Compared with control LNCaP xenografts, LM10-treated xenografts also significantly reduced the mRNA levels of TDO2, AhR, CYP1A1 and CYP1B1 in castration-recurrent tumours." (PMID 40759641, 2025). "Its key rate-limiting enzymes, indoleamine 2,3-dioxygenase (IDO) and tryptophan 2,3-dioxygenase (TDO), are highly expressed in various tumors, leading to tryptophan depletion and the accumulation of metabolites such as kynurenine in the tumor microenvironment." (PMID 41050671, 2025). "In the CRC cohort, enzymes of the KYN pathway, including TDO2 and KMO were upregulated in early-stage tumour tissues, consistent with previous studies." (PMID 40348885, 2025).